INS (insulin)
Diseases named in the same sentence as INS in open-access papers (continued):
Sharing a sentence is not in itself a finding about the gene and the disease.
diabetes (continued). "These setbacks incurred in an attempt to better manage diabetes, together with past innovative strategies, have encouraged science and the clinical community to continue to endeavour for an ideal insulin analogue that demonstrates heightened pharmacokinetic profiles and thermal stability." (PMID 41155876, 2025). "However, advancements such as continuous glucose monitoring and automated insulin delivery have simplified diabetes management and improved QoL for TP patients." (PMID 40987989, 2025). "Despite the lack of direct evidence linking extended sleep duration to the prevention and treatment of diabetes, there are indications that alleviating sleep deprivation may improve insulin sensitivity." (PMID 40421240, 2025). "Present diabetes management technology, particularly advanced hybrid pumps that enable semi-automatic glucose control throughout the day, significantly enhances the ability of insulin-treated ATCOs to maintain optimal glucose ranges." (PMID 41007688, 2025). "We report the case of a 69-year-old male with a history of diabetes mellitus managed with insulin, semaglutide, and empagliflozin, who presented with syncope, bradycardia, and gastrointestinal symptoms following antibiotic treatment for a lower extremity infection." (PMID 40741547, 2025). "Additionally, it improves lipid metabolism, stimulates insulin release, and enhances glucose uptake, aiding in diabetes and metabolic syndrome management." (PMID 40149610, 2025). "However, in the later stages of type 2 diabetes mellitus, serum insulin levels decrease significantly due to impaired β-cell function, including reduced insulin production, impaired proinsulin processing, and amyloid deposition in the islets." (PMID 40453670, 2025). "Analysis of factors regulating the insulin biosynthesis and maturation of β-cells may be useful for the development of new approaches for diabetes therapy." (PMID 39860066, 2025). "Her diabetes was managed with a low-dose insulin sliding scale and long-acting insulin." (PMID 41487744, 2025). "Previous investigations have indicated that A. digitata fruit may aid in the management of diabetes through various mechanisms, including the modulation of glucose transport and insulin signaling pathways." (PMID 41234539, 2025). "In diabetes, calcium homeostasis is often disrupted, with hyperglycemia being a key factor influencing calcium imbalances in critical organs such as skeletal muscles, the liver, heart, and brain, all of which respond to insulin." (PMID 40792127, 2025). "Patients prescribed insulin may have a longer history of diabetes and more severe complications, which could increase their risk of gastrointestinal issues." (PMID 40471297, 2025). "The reason for the higher proportion of diabetes patients in aTRH may be closely related to the reduced insulin secretion and insulin resistance in diabetes patients." (PMID 41048217, 2025). "These include differentiated service delivery models, a structured record that incorporated the National guidelines for the management of patients with diabetes in South Africa, a chronic disease outreach program, the Tshwane Insulin Project, and other video-based group sessions." (PMID 41007478, 2025). "People living with type 2 diabetes are often prescribed multiple non‐insulin anti‐diabetes medications, such as metformin, sulfonylureas, sodium‐glucose cotransporter‐2 (SGLT2) inhibitors, dipeptidyl peptidase‐4 (DPP‐4) inhibitors and glucagon‐like peptide‐1 receptor agonists (GLP‐1 RAs)." (PMID 40851538, 2025). "Future research is warranted to fully understand these nuanced associations and should investigate the interactions between insulin delivery methods, diabetes self-management behaviors, and neurocognitive outcomes, using longitudinal designs and real-time glucose monitoring." (PMID 40873949, 2025).
diabetes (continued). "Even individuals without diabetes who have intact insulin production have been demonstrated to be at risk for euDKA when triggered by stress and reduced oral intake." (PMID 40900206, 2025). "Antibiotic therapy enhanced insulin signaling in diabetes-prone C57BL/6J mice fed a high-fat diet." (PMID 40437354, 2025). "T1DM is typically caused by the impairment of insulin production, resulting from the disruption of pancreatic β-cells as a consequence of T-cell-mediated autoimmunity, while T2DM is the predominant type of diabetes, characterized by insulin resistance (IR)." (PMID 41007838, 2025). "Switching to long-acting insulin analogs, once-daily oral medications, or agents with lower hypoglycaemic risk, such as metformin, SGLT2i or GLP-1 RA, can help reduce the complexity of diabetes management." (PMID 40014274, 2025). "In addition, GLP-1R has been suggested to play a neuroprotective role in diabetes-related neurodegeneration by increasing insulin sensitivity." (PMID 40274715, 2025). "In addition, BMI (β = 0.006, p = 0.045), diabetes duration >10 years (β = 0.094, p = 0.009), and insulin use (β = 0.121, p = 0.003) emerged as significant predictors of higher ΔHbA1c." (PMID 41008733, 2025). "In addition, it has been reported that natural extracts exert hypoglycemic effects by increasing insulin levels and downregulating osteoclastogenesis, processes which, in turn, prevent diabetes-induced osteoporosis." (PMID 40243576, 2025). "Timely initiation of insulin therapy is vital in patients with type 2 diabetes mellitus." (PMID 40336418, 2025). "Insulin, a peptide that promotes bone development, is raised in diabetes." (PMID 40014782, 2025). "Additionally, microneedles are being explored for transdermal insulin delivery in diabetes management, enabling controlled release and reducing the need for repeated injections." (PMID 40336019, 2025). "The review also examines advancements in insulin therapy, technological innovations in diabetes care, and psychosocial interventions that may enhance treatment adherence and quality of life for adolescents with T1D." (PMID 40217595, 2025). "have antioxidative and anti-diabetes properties which could have facilitate glucose uptake by modulating insulin-independent pathways." (PMID 40869081, 2025). "Insulin therapy is frequently required when glucose disturbances progress to overt diabetes." (PMID 39997354, 2025). "Small-molecule pharmacological inhibitors of DYRK1A, such as harmine, are actively being developed for the treatment of diabetes, because they promote expansion of insulin-secreting pancreatic ®-cells and appear well-tolerated in both animal models and human volunteers." (PMID 39896677, 2025). "T2DM, the predominant form of diabetes mellitus, is generally characterized by chronic hyperglycemia, hyperinsulinemia, dyslipidemia, as well as lipotoxicity, which result in progressive deterioration of insulin secretion and insulin action." (PMID 40416375, 2025). "Therefore, the search continues for molecules that can exert a direct positive impact on insulin signaling and β-cell function, with the goal of preventing the progression of metabolic diseases such as diabetes and cardiovascular disease." (PMID 41155548, 2025). "The proportion of people with diagnosed diabetes who are receiving drug therapy has increased over time, though there were medication class trends with increased use of metformin, insulin, GLP1RA, and SGLT2i, and decreased use of thiazolidinediones and sulfonylureas." (PMID 40736548, 2025). "Liver lipids influence hepatic insulin sensitivity and may contribute to the development of diabetes." (PMID 40021748, 2025). "Indeed, in addition to weekly insulin formulations (i.e., icodec), another novel advancement coming in diabetes management for frail patients is the development of long-acting basal insulin analogs with extended duration of action." (PMID 40014274, 2025).
diabetes (continued). "The detected link between BChE and insulin resistance in our study is consistent with the results of smaller studies involving patients with and without overt diabetes, where BChE activity was found to be negatively associated with insulin sensitivity." (PMID 40243328, 2025). "Common diabetes medications, including sliding-scale insulin, sulfonylureas, and SGLT2 inhibitors, are considered potentially inappropriate for older adults due to the risk of hypoglycemia and other adverse effects, which may impact adherence." (PMID 41280553, 2025). "The findings of the present umbrella review suggest that vitamin D supplementation could decrease levels of FBS, insulin, HbA1C, and serum TG in prediabetic patients but fail to reduce HOMA-IR, 2 h-PG, HOMA-B, BMI, and diabetes risk in these patients." (PMID 40813680, 2025). "Furthermore, circulating levels of AREG were significantly higher in obese diabetes than the obesity, probably owing to the higher demand for insulin in T2DM." (PMID 39981678, 2025). "One such cytokine that attained more focus recently is an important adipokine namely chemerin which is involved in both diabetes and periodontal diseases because of its considerable effects on insulin sensitivity, glucose levels, lipid metabolism, and inflammatory disease process." (PMID 40771657, 2025). "This is in keeping with data from adults and other diabetes technology, such as insulin pumps." (PMID 40496819, 2025). "An extensive review of preclinical and clinical studies evaluates the efficacy, safety, and long-term effects of ASs in glycemic control, highlighting their ability to reduce caloric intake, promote satiety, and support glycemic control and insulin sensitivity in individuals with diabetes." (PMID 40873447, 2025). "This required understanding the PWDI's usual insulin regimen and their diabetes management plan." (PMID 40324886, 2025). "The American Diabetes Association (ADA) and the American Association of Clinical Endocrinologists (AACE) recommend monitoring blood glucose levels every hour in critically ill patients receiving intravenous insulin infusion." (PMID 40901501, 2025). "Measurement Limitations: While the DTSQ effectively evaluates satisfaction with diabetes technologies (e.g., insulin pumps, CGM), its psychometric properties remain unvalidated in surgical populations, and potential nonresponse bias merits consideration when interpreting satisfaction metrics." (PMID 40568192, 2025). "However, tissues targeted by insulin should be studied in depth by explaining the differences among endophenotypes of patients with diabetes." (PMID 41373473, 2025). "Findings regarding hyperthyroidism were more nuanced: although no DCM cases were observed in the hyperthyroid subgroup with insulin-treated diabetes, this could reflect the small subgroup size." (PMID 41153651, 2025). "Additionally, patients with a longer duration of diabetes and those using insulin showed poorer glycemic control, but this finding also lacked statistical significance." (PMID 40453275, 2025). "A metabolic condition with numerous etiologies, diabetes mellitus (DM) is defined by an elevated blood glucose level and abnormalities in the metabolism of carbohydrates, fats, and proteins as a result of problems in insulin secretion, insulin action, or both." (PMID 40416402, 2025). "Diabetes resulting from a deficiency of insulin secretion, but not from the deficient insulin action, is classified as type 1 diabetes (T1D)." (PMID 40244115, 2025). "Interestingly, atorvastatin, combined with exogenous LDL-C, impairs glucose-stimulated insulin release (GSIR) but promotes cell proliferation, highlighting a potential mechanism for statin-associated diabetes." (PMID 40090035, 2025). "It has been noted that higher prolactin levels in older individuals without diabetes are associated with improved insulin sensitivity and lower glycemic values." (PMID 40650124, 2025).
diabetes (continued). "We assessed whether time spent in hypoglycemia and hyperglycemia during FCL insulin delivery in adults varied by type of diabetes over the 24-hour period." (PMID 38613227, 2025). "To investigate the influence of the MoKaRi intervention on diabetes risk we analysed fasting glucose, insulin, and calculated HOMA-IR which have not worsened over the 20 and 40 weeks of the MoKaRi study." (PMID 40057729, 2025). "The aim of our analyses was to evaluate whether the use of ESYSTA leads to improvements in self‐management and in glycemic control in insulin‐treated people with diabetes, expressed by a change in HbA1c (in percentage points)." (PMID 41497476, 2025). "Hepatic insulin resistance, a hallmark of NAFLD, disrupts systemic metabolic balance by impairing glucose uptake and promoting hepatic gluconeogenesis, thereby exacerbating hyperglycemia and insulin demand, which accelerates the onset of diabetes and cardiovascular complications." (PMID 40642596, 2025). "Overall, the present real‐world study supports previous evidence from an RCT and a real‐world study with a matched controlled group that the digital device ESYSTA is associated with significant and continuous reductions in HbA1c levels in T1D and T2D insulin‐treated people with diabetes." (PMID 41497476, 2025). "Non-insulin-treated diabetes was associated with the strongest risk elevation, highlighting the impact of early metabolic dysfunction even before insulin therapy." (PMID 41153651, 2025). "We have studied metabolic, anthropometric, and physiological features by analyzing lipid and carbohydrate metabolism with checking diabetes-related indexes (insulin and HbA1c), and physiological parameters such as BP, which is important to the whole body's functionality." (PMID 40989083, 2025). "This reduction in BCAAs in the insulin-resistant state suggests a shift from amino acid accumulation, typical of early obesity-related metabolic stress, toward enhanced catabolism and metabolic reprogramming in overt diabetes." (PMID 41002949, 2025). "Additionally, by increasing insulin production, SchB has been shown to delay the onset of diabetes significantly." (PMID 40703755, 2025). "We aim to publish this data-supported CDCES protocol to facilitate use at other diabetes centers who may restrict CDCES from adjusting insulin doses." (PMID 41283065, 2025). "The possible reasons for this observation could be the pathophysiological interplay between diabetes and hypertension that results in increased insulin resistance and the interactions between medications used for managing both conditions." (PMID 40078898, 2025). "For instance, cells that produce insulin in people with diabetes, or cells that produce recombinant proteins and antibodies that act as immune system inhibitors, could be used to treat patients with autoimmune diseases or cancer." (PMID 39997140, 2025). "Diabetes mellitus (DM) is a metabolic disorder of complex etiology characterized by chronic hyperglycemia with disturbed metabolism of carbohydrate, fat, and protein resulting from defects in insulin secretion, insulin action, or both." (PMID 40937402, 2025). "The skeletal muscle is another insulin-sensitive tissue negatively affected by diabetes." (PMID 40806520, 2025). "Diabetes mellitus (DM) is a prevalent metabolic disorder that poses significant health challenges worldwide and is characterised by chronic hyperglycaemia resulting from defects in insulin secretion, action, or both." (PMID 39982365, 2025). "A clearer understanding of the connection between insulin and bone offers valuable insights for developing targeted strategies to predict, prevent, and manage skeletal complications, particularly among individuals with diabetes mellitus." (PMID 40564223, 2025). "This association likely signifies greater diabetes severity, longer duration, or poorer beta-cell function in insulin-requiring patients, rather than a direct effect of insulin on thyroid function." (PMID 41306154, 2025).
diabetes (continued). "Furthermore, cinnamic acid enhances metabolic health by improving glucose uptake and insulin sensitivity, showing promising results in improving metabolic health in patients with diabetes and its complications." (PMID 40872532, 2025). "For instance, metformin, a diabetes medication, can enhance insulin sensitivity, while statins may influence triglyceride levels." (PMID 40520776, 2025). "Diabetes is a disease that is characterized by chronic hyperglycaemia and impaired glucose metabolism due to insufficient or missing endogenous insulin production and/or decreased sensitivity to insulin." (PMID 40481272, 2025). "Daily diabetes-care behaviors—including blood glucose monitoring, insulin administration, and management of diet and activity—are required to manage blood glucose and prevent short-term (e.g., hypoglycemia, hyperglycemia) and long-term complications (neuropathy, retinopathy, nephropathy)." (PMID 40982726, 2025). "Diabetes duration and insulin use emerged as stronger predictors of remission than procedure type." (PMID 41231326, 2025). "The effectiveness of diabetes camps on mental health may also be significantly influenced by the use of insulin pumps among the camp participants." (PMID 40303940, 2025). "By suppressing NLRP3 activation, EGCG may improve insulin signaling and glucose tolerance, providing further evidence of its potential to alleviate diabetes symptoms." (PMID 39942757, 2025). "Low engagers also expressed fears that engaging in a program to prevent diabetes could progressively lead to overtreatment, and ultimately to requiring insulin." (PMID 40531536, 2025). "However, data on the usefulness and effectiveness of AHCLs in the early stages of diabetes, when insulin requirements are low and residual insulin secretion is present, are still lacking." (PMID 40529832, 2025). "Direct costs for diabetes management constitute a substantial component of financial toxicity and include expenses for medications (particularly insulin), glucose monitoring supplies, devices, and healthcare services for routine disease management and treating complications." (PMID 40358737, 2025). "To further investigate whether inhibiting BACE1 could enhance insulin sensitivity and alleviate symptoms of diabetes, we treated HFD mice with the BACE1 inhibitor Elenbecestat." (PMID 40507910, 2025). "Moving on in months or years when pre‐breakfast glucose control cannot be achieved despite the pushing of basal insulin doses to high levels (>150 U/day), or where problems such as hypoglycaemia intervene, does require more expertise than in usual outside diabetes specialist teams." (PMID 40035222, 2025). "In summary, plant-derived antioxidants target multiple molecular mechanisms central to the pathogenesis of type 2 diabetes mellitus, including impaired insulin signaling, oxidative stress, inflammation, mitochondrial dysfunction, and dysregulated adipokine signaling." (PMID 40563357, 2025). "While SGLT2 inhibitors have become widely used in adults, until 2019 with the advent of glucagon-like peptide-1 (GLP-1) receptor agonists such as liraglutide, the only approved treatments for pediatric patients/children with type 2 diabetes mellitus (T2DM) were insulin and metformin." (PMID 39950157, 2025). "When CRHR1 and the GHRH receptor are activated in pancreatic islets, they stimulate insulin synthesis and alter glucocorticoid balance, which may contribute to the development of diabetes mellitus." (PMID 41294018, 2025). "Additionally, transcription factor 7‐like 2 (TCF7L2) Gene, a major regulator of insulin production and processing, has been considered a prominent marker in individuals with Type 2 diabetes who have a positive family history of diabetes." (PMID 40820550, 2025).